IL15 (interleukin 15)
Diseases named in the same sentence as IL15 in open-access papers (continued):
Sharing a sentence is not in itself a finding about the gene and the disease.
Cachexia (12 papers, 2000 to 2026). Severe weight loss, wasting of muscle, loss of appetite, and general debility related to a chronic disease. "At T2, cachexia was associated with higher mtDNA levels (OR 2.13; 95% CI 1.07-7.69; p = 0.022) and lower levels of IL-15, IL12/IL23p40, and MDC." (PMID 41749907, 2026). "However, TNFα can also cause cachexia that may explain the decrease in the body fat of rodents treated with IL-15." (PMID 27684068, 2016). "At T1, cachexia was strongly associated with elevated GDF15 (OR 4.29; 95% CI 1.04-29.74; p = 0.044) and IL-15 (OR 43.83; 95% CI 2.39->999; p = 0.007), whereas IL-4 had a protective association (OR 0.09; 95% CI 0.00-0.66; p = 0.013)." (PMID 41749907, 2026). "Previous studies have reported that IL-15 can downregulate protein degradation in skeletal muscle from hepatitis-induced cachexia rats, regarded as an approach for the body to antagonize muscle atrophy during cachexia." (PMID 39404384, 2024). "This rise in IL-15 values among patients who gained weight, along with its correlation with body weight and muscle mass, suggests a possible connection between IL-15 and body composition in cancer cachexia patients." (PMID 37755304, 2023). "Both cachexia and pre-cachexia are frequently associated with inflammation; an imbalance between pro-inflammatory (TNF-α, Interleukin (IL)-6, and IL-1) and anti-inflammatory (e.g., IL-4, IL-12, IL-15) cytokines is considered to contribute to the pathogenesis." (PMID 25988122, 2014). "The present study was aimed at investigating if IL-15, which is known to favour muscle fibre hypertrophy, could antagonize the enhanced muscle protein breakdown in this cancer cachexia model." (PMID 10945502, 2000). "Moreover, IL-15 appears to play a role on the preservation of body mass and fat-free mass and the reduction of this cytokine in patients with cancer is related to the development of cachexia." (PMID 31741709, 2019). "Furthermore, exercise-derived myokines such as IL-7, IL-15, and IL-6 act systemically, promoting T cell and NK cell survival while simultaneously exerting anti-inflammatory effects that may mitigate cancer-related cachexia and support immune competence." (PMID 41562839, 2026). "Of these six cytokines, IL-6, IL-8, IL-10, and IL-15 at baseline, and IP-10 at both baseline and during treatment were significantly higher in patients with cachexia than those without." (PMID 36831513, 2023). "Additionally, IL15 has been shown to either suppress or counteract the negative effects of TNFA in human myogenesis, myotube development and function in mouse models of sarcopenia and cachexia." (PMID 30158466, 2018).
depression (12 papers, 2015 to 2025). "Low bodyweight was negatively correlated with increased IL-15 serum levels at admission, whereas IL-15 was positively correlated with illness duration and depression scores." (PMID 38892530, 2024). "Specifically, IL-15 crosses the blood–brain barrier and modulation of IL-15/IL-15rα impacts sleep patterns, anxiety behavior pathways, and anti-depression pathways, which collectively has profound global impacts." (PMID 34326778, 2021). "Yet, the disturbance that we found in IL-15 and its involvement in depression comprise a very important issue to clarify in further studies." (PMID 30662368, 2018). "Age, gender, education, ethnicity, depression and batch effect of IL-15 measurement were adjusted for their potential confounding effects on observed variables." (PMID 25710473, 2015). "Increases in IL-15 and IL-7 might be attributed to T-cell growth, which may equate with increases in monoamine activity, even in individuals with minor reductions in depression severity." (PMID 33276697, 2020). "Moreover, contrary to most of the proinflammatory cytokines analyzed in this work (except IL-15), which seem to have promoting effects towards depression, IL-4 appears to have beneficial effects upon psychiatric disorders in addition to the obvious anti-inflammatory effects." (PMID 30662368, 2018). "In our review, we noticed that IL-15 increased with the administration of the SSRI escitalopram (one study, moderate depression), while it decreased with fluoxetine (one study, depressed patients, week 4)." (PMID 40573262, 2025). "STRING analysis further underscored the shared roles of proteins IL15, C–C Motif Chemokine Ligand (CCL)−2 and CCL20 in the context of air pollution-induced depression and anxiety, potentially highlighting EGFR's critical role in depression." (PMID 40611827, 2025). "Conversely, in males, inflammation was inversely associated with depression severity, with protective effects from regulatory mediators (IL-2, IL-4, IL-6, IL-15, LIF, TNF-α, β-NGF) against depression." (PMID 40305313, 2025). "Furthermore, STRING analysis underscored the shared roles of specific proteins, including EGFR, IL15, CCL2, and CCL20, in the context of air pollution-induced depression and anxiety, highlighting the involvement of immune-related processes and pathways." (PMID 40611827, 2025). "A recent study investigated associations between levels of six cytokines (IL-1β, eotaxin, IL-15, IL-6, TNF-α, and leptin) and chronic multisite pain (CMP) in a sample of people living with HIV, but also incorporated PHQ-9 scores as a measure of depression in their regression models." (PMID 35618889, 2022). "An early study of 23 people living with HIV measured plasma concentrations of several inflammatory cytokines (IL-15, IP-10, IL-12, and G-CSF) and found that these cytokines were significantly elevated in HIV+ individuals with depression compared to HIV+ individuals without depression." (PMID 35618889, 2022).
tuberculosis (12 papers, 2011 to 2025). A chronic, recurrent infection caused by the bacterium Mycobacterium tuberculosis. "In conclusion, the integration of IL-7 and IL-15 with existing tuberculosis vaccines has shown significant promise in enhancing immune responses and strengthening the defense against M. tuberculosis infections." (PMID 38793728, 2024). "The potential of rAd-IL-7-Linker-IL-15 to augment the efficacy of tuberculosis subunit vaccines relies on its ability to strengthen central memory-like T cells, thereby providing enduring protection against M. tuberculosis." (PMID 38793728, 2024). "Therefore, fusion cytokine IL-7-Linker-IL-15 developed as an adjuvant need to be explored for triggering a stronger long-term cellular immune response against tuberculosis." (PMID 33271822, 2020). "For the first time, our study demonstrates that supplementation of TB protein-subunit vaccine with rAd- IL-7-Linker-IL-15 would induce more TCM like cells and improve its protective efficacy against M. tuberculosis." (PMID 33271822, 2020). "Interleukin (IL)-15 and IL-32 play roles in the vitamin D-mediated tuberculosis (TB) defense mechanism." (PMID 30760247, 2019). "The effect of IL-15+ IL-12 on NK cell populations of HIV-TB patients is minimal probably due to the influence of tuberculosis." (PMID 22715368, 2012). "Subsequently, we further verified the transcription levels of genes on anti-tuberculosis-related genes such as CCL1, IL15, IL16, ISG15, GBP5, IL23, ATG2A, IFNβ, and CSF3." (PMID 38392218, 2024). "Rv1476 overexpression inhibited the expression of some anti-tuberculosis-related genes, such as CCL1, IL15, IL16, ISG15, GBP5, IL23, ATG2A, IFNβ, and CSF3." (PMID 38392218, 2024). "The expression levels of certain genes related to anti-tuberculosis were further confirmed, such as CCL1, IL15, IL16, ISG15, GBP5, IL23, ATG2A, IFNβ, and CSF3." (PMID 38392218, 2024). "IL-15+IL-12 is not likely to be of value when co-infected with TB probably due to the influence of tuberculosis." (PMID 22715368, 2012).
ZIKV infection (12 papers, 2017 to 2025). "Adult ZIKV infection is associated with immune activation with upregulation of cellular markers, including CD69, Ki67 and increases insoluble markers, including MCP-1, IL-2, IL-15, vascular endothelial growth factor (VEGF) and IL-10 in the first few days post-infection." (PMID 35130924, 2022). "Since microglial cells play a major role in the inflammatory events from CNS, the binding of autoantibodies to GD3 may prevent the interaction of this ganglioside to IL-15 thus potentiating the inflammatory processes and outcome of CNS tissue damage during ZIKV infection." (PMID 29594116, 2018). "Adult patients in the acute phase of ZIKV infection produce high levels of chemokines such as CXCL3, CXCL9, CXCL10 and IL15 in the serum, as well as microcephaly babies in the cerebrospinal fluid, especially when developing neurological symptoms." (PMID 36142200, 2022). "In general, ZIKV infection elicited rapid increase in serum cytokines and chemokines (specifically IFNγ, TNFα, MCP-1, IL-15, IL-10, IL1RA, MIP-1β), with responses peaking around 1–2 days post-infection." (PMID 34120576, 2021). "IPA also predicted many cytokines, including IL-15, IL-27, IL-32, C5, IL-18, and EB13, were significantly up-regulated by ZIKV infection in HSerC." (PMID 32511241, 2020). "Using a qRT-PCR assay, high expression levels of pro-inflammatory cytokine genes, including IL6, IL15, IFNγ, TNFα, CXCL15, IL18, and IL1β, were confirmed in ZIKV-infected placentas, suggesting that ZIKV infection may trigger placental inflammation." (PMID 41263557, 2025). "Altogether, ZIKV infection led to an increase in IL-1ra, IL-15, and MCP-1 in all infected animals relative to negative control animals, but only MCP-1 differed between cohort A and ZIKV control animals." (PMID 31369649, 2019). "ZIKV infection triggered the upregulation of multiple cytokines in humans during acute phase of infection that we were able to characterize by Luminex assay, including IP-10, IL-5, GM-CSF, TNF-α, IL-15, IL-10, MIP-1α, IFN-γ, IL-6, IL-1RA, IL-2, MIG, IFN-α, IL-2R, and IL-4." (PMID 30333476, 2018).
bladder cancer (11 papers, 2016 to 2025). "TRMs isolated from bladder cancer patients proliferate and upregulate T-bet, perforin, and granzyme B in response to IL-15 stimulation." (PMID 41479900, 2025). "This potential antineoplastic effect has led to the development of an IL-15 superagonist, which has shown clinical efficacy in phase I and II studies in lung and bladder cancer patients." (PMID 36831406, 2023). "More recent novel immunotherapy drugs (e.g., ALT-801 (a tumor-targeted IL-2) and ALT-803 (an IL-15 superagonist complex)) have been tested in bladder cancer with promising antitumor activity." (PMID 29358573, 2018). "Using an intravesical liposomal gene delivery approach in a mouse bladder cancer model, IL-15 gene therapy has been demonstrated to be a new promising approach for bladder cancer treatment." (PMID 27273619, 2016). "In this regard, we showed the strong anti-tumor effects of baculoviral vector-mediated CD40L or IL-15 expression in an animal model with aggressively growing bladder cancer." (PMID 27273619, 2016). "One IL-15 agonist was recently approved by the FDA for the treatment of bladder cancer." (PMID 40149931, 2025). "IL-15 superagonists like N-803-modified IL-15 potently stimulates NK and CD8 T cells, showing promise in other cancers, including bladder cancer when combined with BCG." (PMID 40227782, 2025). "In bladder cancer, TRMs can be activated by anti-CD3, anti-CD28, and IL-15 stimulation, leading to proliferation and increased T-bet, perforin, and granzyme B expression, particularly in the PD-1+ subset." (PMID 41479900, 2025). "An initial screen included a bladder cancer panel with 16 proteins (MCP‐1, MIP‐1α, MIP‐1β, IP‐10, IFN‐α, IL‐1α, IL‐1RA, IL‐8, IL‐7, IL‐31, IL‐15, TNF‐β, Eotaxin, SDF‐1α, Rantes, and GRO)." (PMID 38553868, 2024). "Although the mechanism of their interaction is still unclear, the baculoviral transduction-mediated co-expression of IL-15 and CD40L, as demonstrated in the current study, exhibits potent therapeutic efficacy for bladder cancer." (PMID 27273619, 2016). "N-803, for example, is an IL-15 agonist developed by ImmunityBio; its combination with BCG has been shown to be effective for patients with BCG-unresponsive bladder cancer; 71% of patients who had failed with previous therapies show a complete response with a median duration of 26.6 months." (PMID 39335665, 2024). "Based on the fact that modulation of cytokines is important in cancer therapy, especially in the metaphylaxis of early stage bladder cancer, we investigated the effect of OR10H1 activation on the synthesis of cytokines, which revealed a significant increase in IL10 and IL15 upon stimulation." (PMID 29867524, 2018).
coronary artery disease (11 papers, 2014 to 2026). "The IL15 rs10519613 is located at exon 6, 83 bp behind the stop codon, and the AA+AC genotypes and the allele A of this SNP were found as risk factors for coronary heart disease." (PMID 39844838, 2024). "Contextually, serum IL-15 concentrations are significantly higher in patients with coronary artery disease (CAD) than in healthy subjects." (PMID 34095164, 2021). "Circulating IL-15 levels are shown to be higher in overweight patients exhibiting increased abdominal adiposity and suffering from coronary artery disease." (PMID 27684068, 2016). "Previous studies indicated that IL-15 is expressed by inflammatory cells located at vulnerable atherosclerotic plaques and serum IL-15 concentration is significantly higher in patients with coronary artery disease (CAD) or peripheral artery disease than healthy people." (PMID 24603895, 2014). "On the contrary, our data were derived by exploring the serum concentrations of IL-15 in patients who did not present with established coronary heart disease." (PMID 34095164, 2021). "Similarly, patients with coronary artery disease had a higher IL-15 and IL-15α, along with increased abdominal fat accumulation, compared to patients without coronary artery disease, suggesting that adipose tissue rather than muscle tissue, may be the primary source of IL-15 production." (PMID 40642656, 2025).
dengue (11 papers, 2013 to 2025). "Our finding is consistent with other studies in association of IL-6, IL-8, IL-15, MCP-1, and TNF-α in dengue fever." (PMID 30626045, 2019). "The higher IL-15 levels observed in dengue patients may contribute to an expansion of cytolytic natural killer cells, which can have both antiviral and tissue-damaging effects." (PMID 35631079, 2022). "High levels of IL-15, IP-10 and G-CSF in cluster C suggest that extensive activation of the innate immune system may contribute to the cytokine storm in severe dengue." (PMID 23717702, 2013). "Indeed, IL15 levels found during acute dengue may promote NK cell subset expansion." (PMID 29038620, 2017). "IFN-α, IL-10, IL-12 IL-15, IP-10, MIG and MIP-1β were significantly increased or decreased in dengue patients compared to healthy controls if patients were classified according to the 2009 WHO classification." (PMID 23717702, 2013). "Levels of IL-10, IL-15, VEGF, G-CSF and IP-10 were increased in ‘severe dengue’ cluster C in the cluster analysis." (PMID 23717702, 2013). "Moreover, serum levels of IL-15, CCL-2, CXCL-10, and CXCL-11 correlated with dengue severity in humans." (PMID 40934228, 2025). "In this study, the multiplex bead array reported for the first time literature in human patients infected with dengue virus revealed that the GM-CSF, IFN-γ, IL-10, IL-15, IL-8, MCP-1, IL-6, MIP-1β, and TNF-α levels were significantly raised in dengue subjects compared to healthy controls." (PMID 30626045, 2019). "Increased levels of TNF-α, IL-1β, IL-4, IL-6, IL-8, IL-13, IL-15, macrophage migration inhibitory factor (MIF), and chemokines CCL2, CCL4, CCL5, and CXCL10 (IP-10) among others, have been reported in patients with dengue hemorrhagic fever (DHF) when compared to dengue fever (DF)." (PMID 29986388, 2018). "Among the host inflammatory biomarkers, GM-CSF, IFN-γ, IL-10, IL-15, IL-8, MCP-1, IL-6, MIP-1β, and TNF-α levels were significantly increased in dengue with and without warning signs, in severe dengue patients in comparison to healthy controls." (PMID 30626045, 2019). "Using for example the 2009 WHO classification IL-10, IL-15, IP-10 and MIG were significantly elevated in dengue patients compared to healthy controls, but levels were not significantly elevated in severe compared to uncomplicated dengue." (PMID 23717702, 2013).
endometriosis (11 papers, 2013 to 2024). The growth of functional endometrial tissue in anatomic sites outside the uterine body. "Studies have reported elevated levels of IL-15 in the peritoneal fluid and ectopic endometrium of women with endometriosis." (PMID 39767772, 2024). "In the context of endometriosis, elevated estrogen levels promote IL-15 production in ectopic endometrium, thereby stimulating the growth and invasion of ESCs and suppressing the cytotoxic activity of NK cells." (PMID 38542336, 2024). "Expression of cytokines IL-2, IL-6, IL-10, and IL-15 was lower in endometriosis lesions than in eutopic endometrium in the secretory phase." (PMID 35269619, 2022). "IL-1β, IL-6, and IL-15 expressions were lower, and IL-4 was higher in endometriosis lesions compared to that in eutopic endometrium in the proliferative phase." (PMID 35269619, 2022). "The role of IL-15 in angiogenesis and in the proliferation of human endometrial endothelial cells has been documented before, offering a possible explanation for the role of IL-15 in endometriosis." (PMID 33435569, 2021). "However, research by Lin and colleagues found that IL-15 levels were decreased in peritoneal fluid during the advanced stages of endometriosis." (PMID 39767772, 2024). "Currently, there is no reliable information on the influence of IL15 gene polymorphisms on cytokine levels in endometriosis." (PMID 39767772, 2024). "The involvement of IL-15 in angiogenesis and the proliferation of human endometrial endothelial cells has been previously documented, suggesting a potential role for IL-15 in the development of endometriosis." (PMID 39767772, 2024). "IL-15 was increased in follicular fluid (FF) from women with endometriosis, suggesting that IL-15 may have impaired oocyte quality leading to lower fertilization rates." (PMID 35250857, 2022). "However, these levels are inversely correlated with the depth of invasion and disease stage, suggesting a possible role for IL15 in the early pathogenesis of endometriosis." (PMID 23843796, 2013). "Previous studies have demonstrated that elevated expression of IL-6, IL-15, and TGF-β1 in patients with endometriosis can reduce the activity of NK cells." (PMID 38395801, 2024). "There is also a lack of specific sensitivity and specificity values for IL-15 in the context of diagnosing endometriosis, either alone or in combination with other biomarkers." (PMID 39767772, 2024). "Moreover, IL-15, which shows high expression in ectopic endometrium and is regulated by estrogen, can significantly upregulate VEGF-C expression in NK cells, indicating an abundance of VEGF-C in NK cells within endometriosis lesions." (PMID 38542336, 2024).